DICER1 (dicer 1, ribonuclease III)
Diseases named in the same sentence as DICER1 in open-access papers (continued):
Sharing a sentence is not in itself a finding about the gene and the disease.
papillary thyroid carcinoma (continued). "Our findings suggest that complete inactivation of Dicer1 induces DNA damage accumulation and cell death in RET/PTC3-driven papillary thyroid carcinomas." (PMID 41002430, 2025). "Children have a high detection rate (approximately 80–90%) of pathogenic variants in differentiated thyroid cancers (DTC) and are more likely to have gene rearrangements rather than point mutations, among which DICER1 variants are more common than in adults." (PMID 37046700, 2023).
multinodular goiter (22 papers, 2014 to 2025). Nodular goiter characterized by more than one discrete tissue mass. "The most common feature noted in persons harboring a germline pathogenic loss-of-function variant of DICER1 is a thyroid nodule, with more than 50% of females with this variant developing multinodular goiter in their lifetime." (PMID 39963649, 2025). "More recently, studies of primary intracranial sarcomas and multinodular goiter in young adults suggest less than 60% specificity for germline DICER1 variants." (PMID 38084291, 2023). "Specifically, a recent study indicated a correlation between truncating germline DICER1 mutations and familial multinodular goiter, among other cancers." (PMID 29762508, 2018). "Since this first report, Dicer1 mutation has been reported in several tumors, such as Sertoli-Leydig cell tumors, embryonal rhabdomyosarcoma and multinodular goiter; these disorders are now widely recognized as Dicer1-related disorders." (PMID 26308063, 2015). "Despite the Dcr-1 homolog syndrome phenotype being incompletely defined, a DICER1 mutation was suspected when a girl (case 1 patient) of Danish ethnicity presented with both an ovarian Sertoli-Leydig cell tumor and a multinodular goiter at the age of 13 years." (PMID 24708902, 2014). "We report a novel pathogenic DICER1 mutation (p.Ser1216*) in a Danish family associated with ovarian Sertoli-Leydig cell tumor and a multinodular goiter." (PMID 24708902, 2014). "Epidemiological analysis of a large cohort of individuals with one or more DICER1-associated conditions, compared to controls, reveals that by 20 years of age, the cumulative incidence of multinodular goiter or a history of thyroidectomy is 32% in women and 13% in men." (PMID 39860595, 2025). "Moreover, the established association between multinodular goiter and the DICER1 syndrome further substantiates the association between DICER1 mutations and the cystic “ballooning” of colloid." (PMID 32712880, 2021). "An epidemiological study of individuals with one or more DICER1-associated lesions showed that by 20 years of age, the cumulative incidence of multinodular goiter or history of thyroidectomy is 13% in men and 32% in women, with a 16- to 24-fold increased risk of TC over a patient’s lifetime." (PMID 33495912, 2021). "DICER1 mutations and subsequent global downregulation of miRNAs were found in multinodular goiter." (PMID 29762508, 2018). "In addition, a 21-year-old female cousin of the proband who was diagnosed of an embryonal RMS at age 14 and multinodular goiter at age 20, was also germ-line carrier of the DICER1 mutation." (PMID 28222777, 2017). "There is a risk of thyroid cysts developing in childhood or young adulthood with this syndrome, as one study demonstrated that of 25 relatives with DICER1 mutations, six had non-toxic multinodular goiters." (PMID 39963649, 2025). "Our NGS analysis, which covered all known genes associated with multinodular goiter including a battery of thyroid hormone synthesis genes, TSH receptor, and DICER1 showed no additional genetic abnormalities in the patient." (PMID 27703446, 2016). "DICER1 mutations have previously been associated with ovarian Sertoli-Leydig cell tumor (SLCT), nontoxic multinodular goiter (MNG) and multilocular cystic nephroma." (PMID 24708902, 2014). "Prior to or following CN diagnosis, a total of 26 patients (for 17 of whom, the germline DICER1 status was not documented) developed DICER1-related tumors (e.g., PPB, multinodular goiter, embryonal rhabdomyosarcoma, malignant teratoid ciliary body medulloepithelioma, and others)." (PMID 33673661, 2021).
embryonal rhabdomyosarcoma (21 papers, 2015 to 2026). A poorly circumscribed morphologic variant of rhabdomyosarcoma. "The most prevalent tumor types with DICER1 mutations were embryonal rhabdomyosarcoma (ERMS) (n = 47, 59%) and adenosarcoma (n = 22, 28%)." (PMID 38570882, 2024). "Embryonal rhabdomyosarcoma (ERMS) of the uterus has recently been shown to frequently harbor DICER1 mutations." (PMID 33846547, 2021). "DICER1 hot-spot mutations were also found in a single high-grade ovarian sarcoma, one testicular germ-cell and two embryonal rhabdomyosarcomas." (PMID 26087193, 2015). "Notably, we found a potential association between rhabdomyoblastic differentiation in adenosarcomas and DICER1 mutations, which occur in familial and sporadic forms of embryonal rhabdomyosarcomas." (PMID 28267263, 2017). "The presence of embryonal rhabdomyosarcoma with cartilaginous differentiation is suggestive of DICER1 alterations." (PMID 40630346, 2025). "A review of the literature shows that almost all gynecologic embryonal rhabdomyosarcomas reported (outside of the vagina) and 20% of adenosarcomas harbor DICER1 alterations." (PMID 38976022, 2024). "Of the pediatric sarcomas, embryonal rhabdomyosarcoma, notably ERMS of the uterine cervix, must be considered a potential element of germline DICER1 mutation-associated syndromes, which incorporate a range of dysontogenetic manifestations and embryonal cancers." (PMID 26204834, 2015).
Sertoli-Leydig cell tumor (19 papers, 2013 to 2025). A sex cord-gonadal stromal tumor consists of leydig cells; sertoli cells; and fibroblasts in varying proportions and degree of differentiation. "Recent developments in molecular profiling have shown that more than 90% of adult granulosa cell tumors harbor FOXL2 mutations, and more than 90% of Sertoli-Leydig cell tumors have DICER1 mutations." (PMID 39958081, 2025). "Germline pathogenic mutations in DICER1 are associated with different tumor types affecting the female reproductive system; the two most common are Sertoli-Leydig cell tumors (SLCT) and cervical embryonal rhabdomyosarcoma (cERMS)." (PMID 34599283, 2022). "There is ongoing debate in the literature regarding whether DICER1 mutations arise due to the presence of SLCT (Sertoli-Leydig cell tumor) components or if these mutations are universally present across various mixed sex-cord-stromal tumor categories." (PMID 40901169, 2025). "Interestingly, somatic Dicer1 hotspot missense mutations with defective Dicer1 function in 5p miRNA production were commonly found in nonepithelial ovarian tumors, in particular in 60% of Sertoli-Leydig cell tumors, and rarely in epithelial ovarian and endometrial carcinomas." (PMID 27602775, 2016).
colon carcinoma (18 papers, 2008 to 2025). "Our subgroup analysis, which target specific cancer type, revealed that DICER1 rs3742330 AG heterozygotes showed a significantly increased risk of colon cancer." (PMID 26147304, 2015). "It has been demonstrated that miRNAs are associated with the stemness of CSCs in colon cancers, and an impaired DICER1 function has recently been found to promote the stemness and metastasis in colon cancers." (PMID 26064956, 2015). "In addition, the DICER1 rs3742330 AG genotype was associated with a significantly increased risk of colon cancer." (PMID 26147304, 2015). "We then inoculated MC38 colon carcinoma cells subcutaneously in either Dicer1 wild-type (DWT) or DKO mice and observed delayed tumor growth in DKO mice, in agreement with previous studies." (PMID 40475851, 2025). "Recent reports have shown that aurora kinase A (AURKA), IL6R, NUPR1, and DICER1 play important role in the development, progression, and metastasis of a variety of cancers including colon cancer." (PMID 36685857, 2022). "In colon cancer, Dicer1 impairment promoted stemness, induced an epithelial-to-mesenchymal transition, and enhanced metastatic capability of cancerous colon cells." (PMID 34804161, 2021). "Our results showed that Dicer1 expression under hypoxic conditions in colon cancer cells was upregulated." (PMID 33763118, 2021). "Previous studies have shown that inflammation-induced Jak-STAT3 signaling triggers the ubiquitination of DICER1 in cytoplasm by CUL4A to promote the development of colon cancer." (PMID 28420424, 2017). "We addressed this question by transfecting CT26.WT murine colon cancer cells with three different siRNAs targeting Dicer1, respectively." (PMID 25742789, 2015). "DICER1 promoted colon cancer cell invasion by increasing the small non-coding RNA tRF-20-MEJB5Y13." (PMID 35682560, 2022). "DICER1 targeted the miR-200 family to promote the development of colon cancer and metastasis." (PMID 35682560, 2022). "Although Dicer1 displays different expression patterns in different cancers, our data suggest that Dicer1 expression under hypoxic conditions in colon cancer cells was upregulated and it may affect CRC cells and tumor microenvironment." (PMID 33763118, 2021). "Interestingly, we found decreased expression of DICER1 in colon tumors from females." (PMID 19578509, 2008). "Similarly, a weak or negative DICER1 expression correlated with reduced overall and disease-free survival in other malignancies, such as colon cancer and gallbladder cancer." (PMID 26087193, 2015).
glioma (18 papers, 2016 to 2026). A benign or malignant brain and spinal cord tumor that arises from glial cells (astrocytes, oligodendrocytes, ependymal cells). "DYRK1A and DICER1 are involved in neural development and miRNA processing, both of which are dysregulated in glioma." (PMID 40561176, 2025). "MOV10 can bind to circ-DICER1 and modulate the cell viability, migration, and angiogenesis in glioma." (PMID 40061896, 2025). "Silencing of cZNF292, circ‐DICER1, and circ_002136 downregulated glioma tube formation through angiogenesis corresponding genes consisting of EGFR, VEGFRs, SOX13, and ZIC4 in human gliomas." (PMID 37953502, 2024). "RBP MOV10 that bound to circ-DICER1 induced the proliferation, migration as well as tube formation in glioma cells via activation of PI3K/Akt pathway." (PMID 33634155, 2021). "MiR103A-3p also participates in circRNA Dicer1-mediated glioma endothelial cell migration and circRNA TCF25 regulated the invasion and migration of bladder cancer cells." (PMID 34787047, 2021). "This molecular axis of MOV10/circ-DICER1/miR-103a-3p/miR-382-5p/ZIC4 gives novel insights into glioma angiogenesis, providing prospective targets for anti-angiogenesis strategy." (PMID 31937318, 2020). "Recent studies reveal that glioma-exposed endothelial cells (GECs) exhibit high expression of circRNA DICER1 (circ-DICER1) and its RBP MOV10." (PMID 31937318, 2020). "The purpose of this study is to elucidate the potential roles and molecular mechanisms of MOV10 and circ-DICER1 in regulating the angiogenesis of glioma-exposed endothelial cells (GECs)." (PMID 30621721, 2019). "Comparatively, the study in vivo and in vitro demonstrated that the effects of both MOV10 and circ-DICER1 silencing on the angiogenesis of glioma were better than the effects of MOV10 or circ-DICER1 alone silencing." (PMID 30621721, 2019). "MOV10 / circ-DICER1 / miR-103a-3p (miR-382-5p) / ZIC4 pathway plays a vital role in regulating the angiogenesis of glioma." (PMID 30621721, 2019). "In addition, Moloney leukemia virus 10 (MOV10), belongs to the RNA helicase superfamily, can bind to circ-DICER1 and regulate glioma angiogenesis through the circ-DICER/miR-103a-3p (miR-382-5p)/ZIC4 pathway." (PMID 34745938, 2021). "In addition, the binding site of MOV10 and circ-DICER1 was confirmed with the help of CircInteracome database, and the result of RIP demonstrated MOV10 promoted the angiogenensis of glioma by targeting circ-DICER1." (PMID 30621721, 2019). "Consequently, MOV10/circ-DICER1/miR -103a-3p (miR-382-5p)/ZIC4 pathway plays a vital role in regulating the angiogenesis of glioma." (PMID 30621721, 2019). "Circ-DICER1 could regulate the angiogenesis of glioma via sponging miRNAs." (PMID 37407973, 2023). "SNHG18, NEAT1, LINC00339) and low expression of four lncRNAs (DICER1.AS1, NNT.AS1, WAC.AS1, TTC28.AS1 were with poor prognosis in glioma." (PMID 35237509, 2022). "The DICER1 and most of the SDHA and CFTR GV carriers developed glioma after the age of 65 years." (PMID 41546701, 2026). "Circ‐DICER1 was reported that it could interact with miR‐103a‐3p/miR‐382‐5p to inhibit ZIC4, which accelerated Hsp90beta in glioma‐exposed endothelial cells (GECs), and Hsp90 promoted the tumorigenesis of GECs binding to PI3K/AKT signaling pathway." (PMID 37953502, 2024). "Although DICER and global miRNA levels are downregulated in gliomas, complete loss of DICER1 and miRNA expression have not been reported, suggesting that DICER and miRNAs play a critical role in the development of these tumors." (PMID 27421140, 2016).
pineoblastoma (18 papers, 2018 to 2025). Pineoblastoma is a rare, malignant type of supratentorial primitive neuroectodermal tumor (sPNET), found mainly in children (less than 10% of cases are reported in adults), and located in the pineal region of the brain but that can metastasize along the neuroaxis. "Unlike the tumor-specific somatic RNase III hotspot mutation, loss of heterozygosity in the wildtype allele is more common in DICER1-related pineoblastoma than in other entities." (PMID 40361440, 2025). "CNS tumors with DICER1 mutations include pineoblastoma, primary intracranial sarcoma, and pituitary blastoma." (PMID 37173979, 2023). "DICER1 encodes a ribonuclease involved in microRNA processing, and mutations in this gene are a known predisposing factor for pineoblastoma." (PMID 37221626, 2023). "The absence of somatic and germline DICER1 mutations in the present case argues against a link with DICER1‐associated entities such as pituitary blastoma, pineoblastoma, DICER1‐associated CNS sarcoma and embryonal tumour with multilayered rosettes." (PMID 34460114, 2022). "One was a White woman (patient 24) with a history of pineoblastoma (when she was an adolescent) and meningioma (in her 40s) with a germline DICER1 frameshift variant (p.Ser1823Valfs) who died in her 40s; cause of death was not documented in the EHR." (PMID 33630087, 2021). "Pineoblastoma is a rare pediatric cancer induced by germline mutations in the tumor suppressors RB1 or DICER1." (PMID 32286280, 2020). "To date, in DICER1-related pineoblastomas loss of heterozygosity of the wild-type DICER1 allele seems to be the somatic event, in contrast from the typical missense hotspot mutations that usually lead to a factual germline heterozygosity." (PMID 33552988, 2020). "Individuals with pineoblastomas were tested by de Kock and colleagues for the presence of DICER1 mutations." (PMID 29762508, 2018). "Therefore, loss of heterozygosity (LOH) is a rare phenomenon in DICER1 neoplasms, but has been described in pineoblastomas as explained later on." (PMID 40940982, 2025). "Interestingly, two cases initially histologically diagnosed as pineoblastoma and harbouring RNase IIIb domain mutations in DICER1 were by DNA methylation profiling reclassified as ETMRs." (PMID 32601913, 2020). "Patients with germline mutations in DICER1, a ribonuclease involved in microRNA processing, have increased risk of pineoblastoma, but genetic drivers of sporadic pineoblastoma remain unknown." (PMID 30030436, 2018). "They suggested that germline DICER1 mutations make a clinically significant contribution to pineoblastoma; however, additional studies may confirm a causal relationship." (PMID 29762508, 2018). "Additionally, the study of a single patient implicated a DICER1 germline mutation in a pineoblastoma." (PMID 29762508, 2018). "Moreover, somatic DROSHA and DGCR8 mutations, both related to the Dicer miRNA-regulating pathway, have been recently documented in pineoblastomas, in addition to germline and somatic DICER1 mutations, indicating that pineoblastoma development is influenced by disturbances of miRNA processes." (PMID 33552988, 2020). "Further studies may determine the relationship between DICER1 mutations and pineoblastomas." (PMID 29762508, 2018). "Somatic LOH was also observed in the tumor, indicating that DICER1 acts as a tumor suppressor gene in pineoblastoma." (PMID 37221626, 2023). "Together with earlier findings that ETMRs could present with a pineoblastoma-like histology this opens the possibility that the type of aberration affecting DICER1 could influence what type of tumor develops." (PMID 32601913, 2020). "By studying families of patients diagnosed with pineoblastoma and Wilms tumor, they identified DROSHA germline variants in the absence of DICER1 germline variants." (PMID 40940982, 2025).
pineoblastoma (continued). "In fact, the absence of DICER1 and DROSHA mutations differentiates PPTID from pineoblastoma." (PMID 37444483, 2023).